IL6 (interleukin 6)
Diseases named in the same sentence as IL6 in open-access papers (continued):
Sharing a sentence is not in itself a finding about the gene and the disease.
cardiovascular disease (continued). "Inflammatory mediators such as TNF-α and IL-6 released during these conditions are tightly linked to pathological cardiovascular diseases, including drug intoxication." (PMID 34548593, 2021). "Atherosclerotic cardiovascular disease is an inflammatory disorder and both MR studies and randomized controlled trials suggest that inhibition of IL‐6 signalling reduces risk of cardiovascular outcomes and thromboembolic events." (PMID 33393675, 2021). "The present study concludes that AGE lowers IL-6 in females with a risk profile of cardiovascular disease." (PMID 33868439, 2021). "Secondary analysis from CANTOS suggests that the therapeutic benefit of IL-1 inhibition for cardiovascular disease is associated with a reduction in IL-6 levels." (PMID 34504432, 2021). "IL-6 is known as a biomarker of systemic inflammation and is elevated in cardiovascular diseases (CVD) and is also associated with oxidative stress." (PMID 34640478, 2021). "IL-6 is the key pro-inflammatory cytokine and its pathogenic role in the development of cardiovascular disease is well established." (PMID 33761122, 2021). "Several epidemiological studies have highlighted the association between IL-6 signaling and cardiovascular disease onset and complications." (PMID 32485823, 2020). "More broadly, cardiovascular diseases are generally linked to inflammation and increased levels of IL-6 were shown to be significantly associated with a risk of CHD." (PMID 32244351, 2020). "The present conclusions have clinical importance because an elevated IL-6 level can be a risk factor for the development of cardiovascular diseases in adults with OSAS." (PMID 32793188, 2020). "The proatherogenic inflammatory cytokine interleukin-6 (IL-6) was a biomarker of the blood vascular inflammation that was an important risk factor for cardiovascular diseases." (PMID 33029103, 2020). "Low-grade inflammation produced by C-reactive protein (CRP) and interleukin-6 (IL-6) cytokine is a predictor of the risk for cardiovascular diseases." (PMID 30624536, 2019). "The specific objective of this analysis was to clarify the role of 174G>C IL-6 (rs1800795) gene polymorphism in cardiovascular diseases." (PMID 31338006, 2019). "In this study, we found that M-CSF is positively correlated with IL-6 and IL-18, suggesting M-CSF induced activation of IL-6 is related to M-CSF associated cardiovascular disease in patients undergoing maintenance hemodialysis." (PMID 31419967, 2019). "IL-6 is a risk factor associated with cardiovascular disease and is associated with sarcopenia and muscle loss." (PMID 29686666, 2018). "Although IL-1Ra shows a robust association with a number of health risks including cardiovascular disease, its regulation is distinct from that involved in IL-6 expression (Dinarello, 2009, Schaper and Rose-John, 2015)." (PMID 29588232, 2018). "A recent study found close correlation between CRP and IL-6 in patients with high risk of cardiovascular disease." (PMID 29143684, 2017). "In multivariate linear regression analysis, age, sex, cardiovascular disease, and interleukin-6 were independently associated with LTI." (PMID 28448447, 2017). "While animal models provided consistent results for the beneficial consequences of the sgp130fc-induced blockade of the IL-6 trans-signaling, in human studies, the association of sgp130 levels and cardiovascular disease appears less straightforward." (PMID 28250574, 2017). "Among novel cardiovascular disease risk factors,C-reactive protein was 3.3% (95% CI 1.0–5.6%) higher, interleukin-6 was 2.7%(95% CI 1.1–4.3%) higher, and vitamin D was 11.2% (95% CI 1.0–20.4%)lower." (PMID 27899528, 2017). "NF-kB is an oxidant-sensitive transcription factor that plays a key role in the expression of pro-inflammatory genes, including interleukin-6 (IL-6), a multifunctional cytokine that is widely implicated in cardiovascular disease." (PMID 28536613, 2016).
cardiovascular disease (continued). "IH causes a transition to increased circulating TNF-α and IL-6 levels that is a factor in the development of cardiovascular diseases in OSA patients." (PMID 27977796, 2016). "Although, cardiovascular disease and dysfunction are associated with increases in inflammatory cytokines such as IL-6 and IL-18 the large extent of cardiac I/R injury reported here does not correlate with the small changes in circulating cytokines." (PMID 27558113, 2016). "Markers of inflammation are elevated in HIV-infected patients, and elevations in markers such as high-sensitivity C-reactive protein, D-dimer, and interleukin-6 (IL-6) have been associated with increased risk for cardiovascular disease." (PMID 25648075, 2015). "Elevated levels of interleukin 6 (IL-6) and tumor necrosis factor alpha (TNFα), produced by the immune system play an important role in increasing the risk of cardiovascular disease." (PMID 26312203, 2015). "Elevated D-dimer levels have been associated with an increased risk of cardiovascular disease and hsCRP and IL-6 have been associated with cardiovascular disease and opportunistic infection." (PMID 26641655, 2015). "It has long been established that the development of chronic auto-inflammatory conditions, including RA and several cardiovascular diseases, is associated with elevated levels of pro-inflammatory cytokines such as IL-1β, IL-6 and TNF." (PMID 26474486, 2015). "Subjects homozygous for the risk allele (C) of the-174 G/C IL-6 polymorphism have higher levels of IL-6 than do G genotype carriers and a demonstrably increased risk from cardiovascular disease." (PMID 25773008, 2015). "Numerous studies have also shed light on the role of IL-6 in cardiovascular disease, as long-term IL-6 levels are highly associated with HF by prolongation of STAT signaling, especially STAT3, in cardiacmyocytes." (PMID 25122164, 2014). "Separate lines of evidence provide support to the role of genetic variation in IL6 in low grade systemic inflammation and, albeit less consistently, cardiovascular disease risk." (PMID 25133672, 2014). "Systemic chronic inflammation is a risk factor for cardiovascular disease where IL-6 act as central regulator." (PMID 25098735, 2014). "High sensitivity C-reactive protein (hsCRP and interleukin-6 (Il-6) are both well accepted markers of inflammation, related to increased risk of death and cardiovascular disease." (PMID 24505249, 2014). "In a separate cohort, CAP survivors had unresolved inflammation at hospital discharge despite being deemed ready for discharge, and higher IL-6 levels were associated with higher risk of cardiovascular disease–related deaths during the subsequent year." (PMID 25182529, 2014). "High blood plasma IL-6 is a biomarker of cardiovascular disease (CVD) risk in adults, and is associated with increased overall mortality in adults with HIV-1 infection (HIV+)." (PMID 24086545, 2013). "In contrast to geriatric scales, we found history of cardiovascular diseases to be strongly associated for this parameter as for high IL-6 production upon exvivo stimulation with alum." (PMID 24244750, 2013). "One systematic review showed that circulating IL-6 was associated with an increased risk of cardiovascular disease." (PMID 24453409, 2013). "IL-6 in turn can stimulate levels of hsCRP, which is an additional risk factor for cardiovascular disease." (PMID 24391744, 2013). "Associations of hsCRP and IL-6 with each other and with cardiovascular disease (CVD) are well established in the literature." (PMID 24090339, 2013). "Markers of inflammation (such as hsCRP and IL-6) are known to be elevated in HD patients and linked to cardiovascular disease and mortality." (PMID 22732331, 2012). "Inflammatory cytokines associated with increased cardiovascular disease risk, IL6, IL8 and MCP-1 were determined." (PMID 22883023, 2012).
cardiovascular disease (continued). "Parameters of chronic inflammation such as plasma hs-CRP, TNFα and IL-6, which are risk factors for cardiovascular disease, remained unchanged, as did plasma adiponectin, which is thought to reduce the risk for cardiovascular diseases." (PMID 22188761, 2011). "For instance, increased serum IL-6 level has been predictive for risk of cardiovascular disease in the general population, and mortality in HIV+ persons." (PMID 21912648, 2011). "Interleukin-6 (IL-6) and fibrinogen are biomarkers of systemic inflammation that are independent risk factors for cardiovascular disease." (PMID 20056584, 2010). "Inflammatory markers such as high-sensitivity C-reactive protein (hs-CRP), serum amyloid A, interleukin-6 (IL-6), and soluble intercellular adhesion molecule type 1 (sICAM-1), are predictors of risk in patients with cardiovascular disease." (PMID 19222850, 2009). "Interleukin-6 (IL-6) is a well-established, independent indicator of multiple distinct types of cardiovascular disease and all-cause mortality." (PMID 19936194, 2008). "Together, these observations indicate that circulating IL-6 is a marker for common pathophysiologic processes underlying clinically significant cardiovascular disease." (PMID 19936194, 2008). "Elevated levels of IL-6 are associated with the highest risks for subclinical cardiovascular disease as well as for clinical cardiovascular disease in older men and women." (PMID 17374166, 2007). "Elevated levels of IL-6 may affect cardiac electrophysiology and are associated with prolongation of the QT interval in cardiovascular diseases." (PMID 41592077, 2026). "Moreover, serum levels of IL-6 and highly sensitive C-reactive protein (hsCRP) have been independently associated with cardiovascular disease risk." (PMID 40001466, 2025). "Of note, IL-6 is a strong risk marker and a mediator for future cardiovascular diseases." (PMID 40332485, 2025). "Senescent macrophages play a key role in the pathogenesis of cardiovascular disease through the persistent secretion of senescence-associated secretory phenotype (SASP) factors such as IL-6, TNF-α, CCL2, matrix metalloproteinases (MMPs) and reactive oxygen species (ROS)." (PMID 40940785, 2025). "HS‐CRP diagnoses a low‐grade inflammation and is used as a potential biomarker for predicting cardiovascular disease risk, although IL‐6 also may have a prognostic role in subclinical cardiovascular events in high‐risk patients." (PMID 39160453, 2024). "Also, age (OR: 1.06, p = 0.019), IL-6 (OR: 1.44, p = 0.047), and cardiovascular disease (CVD) (OR: 3.66, p = 0.043) were associated with ACS development." (PMID 39395941, 2024). "This anti-inflammatory effect may be related to metformin’s impact on certain inflammatory mediators, such as C-reactive protein and interleukin-6, which are known risk factors for cardiovascular diseases." (PMID 38553738, 2024). "IL-6 may be associated with an increased risk of cardiovascular disease in RA due to its role in systemic and local inflammation." (PMID 38929699, 2024). "Participants in the treatment group demonstrated significantly lower IL-6 post-treatment, indicating lower Cardiovascular disease (CVD) risk, compared to those in the information-support condition; however, these significant reductions did not persist at a 1-year follow-up." (PMID 38300637, 2024). "While increased levels of circulating biomarkers such as IL-6 as well as hs-CRP independently predict the risk of cardiovascular diseases, it remains unclear to what extent they represent local processes occurring in the vessel wall." (PMID 37745103, 2023). "Since inflammatory factors, such as IL1β and IL6, increase risk of cardiovascular diseases, the signaling from ER stress to inflammation induced by the TKIs may be a potential target for treating cardiotoxicity." (PMID 37069550, 2023).
cardiovascular disease (continued). "Some studies have found that biomarkers such as serum B-type natriuretic peptide precursor (BNP),calcitoninogen, cardiac troponin (cTn), highly sensitive C-reactive protein (Hs-CRP), D-dimer, and Interleukin-6 (IL-6) levelsare associated with the occurrence of cardiovascular disease." (PMID 39077519, 2023). "Currently, the clinically approved agents that target this pathway (such as anti-IL-6 therapies) are already available and could reduce the risk of cardiovascular disease in elderly people." (PMID 36835296, 2023). "CRP is primarily under regulation of IL-6 and is widely associated with cardiovascular diseases, since more than 20 large prospective studies suggest that hsCRP could be a predictor of future cardiovascular events." (PMID 37371494, 2023). "Taken together, the current research evidence suggests that high levels of fibrinogen, interleukin-6, C-reactive protein and galectin-3 are risk factors for cardiovascular disease and can be used as biomarkers to predict the development of cardiovascular disease to some extent." (PMID 37485268, 2023). "Previous studies indicated that IL6R p.Asp358Ala [a commonly occurring variant in the IL-6 receptor (IL-6R) gene] could disrupt IL-6 signaling and provide a genetic proxy for tocilizumab, which reduces the risk of cardiovascular diseases in CHIP carriers." (PMID 38104193, 2023). "Il-6 is closely associated with many cardiovascular diseases." (PMID 37047522, 2023). "Moreover, studies on IL-6 gene polymorphism have shown that IL-6 gene polymorphism is related to cardiovascular disease." (PMID 35419117, 2022). "As both a cause and a result of cardiovascular diseases, inflammatory cytokines, such as interleukin-1 (IL-1), interleukin-6 (IL-6), tumor necrosis factor (TNF), galectin-3, and others, have a very significant positive link with the pathophysiology and development of these conditions." (PMID 36186974, 2022). "IL-6 is a pivotal cytokine associated with innate immunity that plays a proatherogenic role in cardiovascular disease, and IL-6 inhibition may be a novel strategy to exert cardiovascular protection." (PMID 35354938, 2022). "On the other hand, interleukin 6 appears to be causally associated with cardiovascular disease." (PMID 35837017, 2022). "The expression of pro-inflammatory cytokines, such as TNF-α, IL-1β and IL-6, has been found to be up-regulated in the large elastic arteries of old mice and humans, and may therefore be associated with age-related cardiovascular disease." (PMID 36465181, 2022). "It has been reported that treatment with canagliflozin improves adipose tissue functions; modifies levels of serum leptin, adiponectin, and interleukin 6; and may favorably affect insulin sensitivity and other risk factors for cardiovascular disease." (PMID 35884961, 2022). "There are many common molecular signaling pathways between COPD and OSA, such as C-reactive protein, interleukin 6, and nuclear factor kappa B. Their interaction can cause a systemic inflammatory response and increase body oxidative stress, leading to cardiovascular diseases." (PMID 34336955, 2021). "Elevated CRP and IL6 levels are associated with various cardiovascular diseases." (PMID 34168680, 2021). "AGE has in prior clinical and preclinical studies shown a beneficial effect on inflammation, with a significant lowering effect on IL-6; however, this is the first time it has been shown to have a lowering effect in a female cohort with a low risk of cardiovascular disease." (PMID 33868439, 2021). "Indeed, it has been demonstrated that cardiac long-term IL-6 signalling or cardiac over production of IL-6R have a causal role in cardiovascular disease." (PMID 34071707, 2021). "This may explain the protective effect of the presence of cardiovascular disease, or the effect of IL-6 levels and cardiovascular disease on VTE risk." (PMID 34948552, 2021). "IL-6 has also been identified as an independent risk factor for cardiovascular disease." (PMID 35366257, 2021).
cardiovascular disease (continued). "IL-6 mediated inflammation is also implicated in cardiovascular diseases which is produced in response to host cell injury, while chronically elevated levels of it could lead to chronic inflammation and fibrotic disorders." (PMID 33827626, 2021). "Therefore, SDG reduces IL-1β, TNF-α, and IL-6 expression, which indirectly reduce the damage of endothelial cells and the risk of cardiovascular disease." (PMID 32684834, 2020). "IL-6 is a key inflammatory factor whose secretion is activated by the C-reactive protein and has been implicated in the pathogenesis and clinical evolution of cardiovascular diseases." (PMID 32455143, 2020). "Genetically determined reduced IL-6 signaling lowers the risk of multiple cardiovascular disease." (PMID 32684834, 2020). "A more direct causal involvement of IL-6 in the pathogenesis of cardiovascular disease may explain the better predictive value of IL-639." (PMID 31341203, 2019). "We have found a statistical association between CA125 and IL-6, supporting the hypothesis that elevated levels of IL-6 in cardiovascular diseases may play a leading role in the stimulation of CA125-producing cells in a damaged mesothelium." (PMID 31058877, 2019). "Hypertrophic adipocytes increase the generation of inflammatory cytokines such as tumor necrosis factor-α (TNFα) and interleukin-6 (IL-6), which may cause chronic inflammation and increase the risk of developing cardiovascular disease." (PMID 31540318, 2019). "Hence, we evaluated the participation of the -174G>C (rs1800795) IL-6 gene polymorphism as a probable risk factor for cardiovascular diseases." (PMID 31338006, 2019). "IL-6 is a confirmed pleiotropic pro-inflammatory cytokine associated with cardiovascular diseases." (PMID 29552316, 2018). "Evidence has also shown that high levels of IL-6 are associated with cardiovascular disease risk." (PMID 30423923, 2018). "While prior studies in SSA have found elevated CRP, IL-6, and other markers of systemic inflammation which were associated with increased mortality and cardiovascular disease, there is a clear need for data on the relationship of inflammation with metabolic comorbidities." (PMID 30009182, 2018). "Prather and colleagues reported that poor sleep quality, especially in combination with greater visceral adiposity, which is a risk factor for metabolic and cardiovascular diseases, was associated with stress-related increases in IL6 levels and IL6/IL10 ratio in postmenopausal women." (PMID 28060925, 2017). "Increased secretion of inflammatory cytokines is thought to be involved in pathogenesis of numerous aging diseases, and clinical trials strongly support a link between increased levels of TNF-α and IL-6 with menopause-related bone loss and cardiovascular diseases." (PMID 26640615, 2016). "Systemic inflammation, as measured by IL-6, may be associated with future cardiovascular events and the clinical evolution of cardiovascular disease in older patients." (PMID 27924924, 2016). "As IL-18 induces the production of TNFα which, in turn, supports the synthesis of IL-6, IL-18 might well be responsible for a high risk of cardiovascular disease in obese patients." (PMID 27747236, 2016). "Interestingly, autonomic dysregulation, expressed as depressed HRV, has been linked to increased IL-6 in healthy individuals as well as in those with a cardiovascular disease." (PMID 23622100, 2013). "Circulating elevated levels of inflammatory markers, such as CRP, TNF-alpha, and IL-6, are associated with increased risk of developing cardiovascular disease; even some acute-phase reactants may also contribute to their pathogenesis." (PMID 23690772, 2013). "Importantly, their study demonstrated a significant association between IL6 and an IL6-smoking interaction in cardiovascular disease." (PMID 23866260, 2013).